HIF1A (hypoxia inducible factor 1 subunit alpha)
Diseases named in the same sentence as HIF1A in open-access papers (continued):
Sharing a sentence is not in itself a finding about the gene and the disease.
melanoma (continued). "The identification of this miR-33a/HIF-1α axis has been proposed to be a novel approach for the management of melanoma." (PMID 28141816, 2017). "A previous publication of our own group revealed constitutively induction of HIF-1α expression in melanoma cells." (PMID 27901477, 2017). "Hypoxia was found to alter the expression of MITF via HIF1α leading to switching of melanoma proliferative to invasive phenotype." (PMID 29383127, 2017). "We observe that drastically smaller tumours from HIF-1α KO mice give rise to a degree of circulating melanoma cells and pulmonary seeds that is comparable to WT tumours." (PMID 29150606, 2017). "Western blot analysis of protein extracts from these melanomas demonstrated increased expression of HIF-1α, HIF-2α, VEGF-A, Snail1, and Oct4 protein in response to sunitinib treatment compared to vehicle controls." (PMID 29383148, 2017). "Despite the differences in tumour size at day 14, the expression of S100B in blood samples from HIF-1α KO, indicative of the number of circulating melanoma cells was found elevated comparable to WT mice." (PMID 29150606, 2017). "In our previous study, we demonstrated that miR-33a functions as a tumor suppressor by targeting HIF-1α in melanoma cells." (PMID 29137372, 2017). "In a similar study, knockdown of HIF-1α by appropriate siRNA in a melanoma cell line decreased the colony formation potential of cells." (PMID 28321776, 2017). "In the highly motile HT168-M1 melanoma cells, where hypoxia increased the mRNA and protein expression of the three small G-proteins and increased the RhoA activation, HIF-1α silencing reverted these changes." (PMID 28562340, 2017). "In our previous study, we showed that miR-33a functions as a tumor suppressor by targeting HIF-1α in melanoma." (PMID 29137372, 2017). "Previous reports have suggested that the pro-angiogenic response of melanoma to low levels of oxygen depends at least in part on HIF1α mediated down-regulation of MITF." (PMID 28380427, 2017). "Dietary OL inhibited HFD-induced accumulation of adipocytes and M2-MΦs, expression of VEGF-A, -D, and HIF-1α in tumor tissues, thereby suppressing tumor angiogenesis and lymphangiogenesis in melanoma-bearing obese mice." (PMID 28410190, 2017). "The liver colonization capacity of melanoma cells, increased by CoCl2 administration, was decreased in the case of HIF-1α silenced cells." (PMID 28562340, 2017). "Again, subcutaneous B16F10 melanomas in HIF-1α KO mice had significantly lower tumour volumes at day 18, without genotype-specific differences in infiltration of immune cell subsets or NK cell activation." (PMID 29150606, 2017). "Because decreased mRNA levels also cause retardation of de novo protein synthesis, we next measured the HIF-1α mRNA levels after vanillin treatment of A2058 and A375 melanoma cells." (PMID 28257048, 2017). "In this study, we demonstrate that vanillin effectively decreases HIF-1α protein levels and the expression of its target genes related to cell motility, angiogenesis, and glycolytic metabolism in A2058 and A375 malignant melanoma cells." (PMID 28257048, 2017). "Our data showed that PDT and respectively Metformin and PDT inhibited the expression of the VEGF and HIF-1α, in the melanoma cells." (PMID 28278159, 2017). "We previously found that the HIF-1α/PDK axis was a major repressor of mitochondrial function in melanoma." (PMID 27250023, 2016). "Our previous study showed that ASS1 expression is positively regulated by c-Myc but negatively regulated by HIF-1α in melanoma cells." (PMID 26771234, 2016). "Together with our recent demonstration of ABCB5-mediated regulation of IL-1β secretion in human melanoma cells, these results suggest that the glycolysis pathway in melanoma cells is potentially regulated by an ABCB5/IL-1β/HIF-1α/PFKP signaling cascade." (PMID 27560924, 2016).
melanoma (continued). "In fact, levels of HIF-1α correlate with melanoma growth, and inhibition of ATR has been shown to increase apoptosis in UV-exposed primary human keratinocytes." (PMID 26824423, 2016). "First, we observed that melanoma metastasis cell lines expressed both cytosolic and nuclear HIF1α when cultured under low oxygen conditions, whereas HIF1α was not detectable when cells were kept in normoxic conditions." (PMID 27426915, 2016). "The addition of ascorbic acid also significantly reduces the transcriptional activity of HIF-1α in WM9 metastatic melanoma cells, resulting in decreased invasive potential." (PMID 26547841, 2015). "Overexpression of HIF1α and HIF2α is linked to VEGF expression and poorer prognosis in malignant melanomas." (PMID 26116372, 2015). "The use of the oxidation-resistant AA analog, A2P, to reduce the ability of HIF-1α to promote malignant progression in melanoma cells and enhance their response to therapy warrants further investigation." (PMID 26547841, 2015). "Further, we showed that A2P, a less oxidizable analog of AA, was more potent than AA in reducing the amount of HIF-1α in the melanoma cells treated with CoCl2." (PMID 26547841, 2015). "Melanoma cells were treated with ascorbic acid (AA) and ascorbate 2-phosphate (A2P) to assess their ability to reduce HIF-1α accumulation and activity." (PMID 26547841, 2015). "We show here that methyl sulfone significantly reduced HIF-1α expression under hypoxia in metastatic breast and melanoma cells." (PMID 26536104, 2015). "Further, the amount of HIF-1α was increased in cells from invasive and metastatic human melanomas relative to that found in cells from radial growth phase melanomas." (PMID 26547841, 2015). "The migration and invasion capacities of vemurafenib-treated melanoma cells were increased, in spite of vemurafenib-decreased expression of HIF1α and CAIX." (PMID 25997619, 2015). "We observed that the expression of HIF1α was inhibited in melanoma cells overexpressing IGFBP5, which is consistent with the inhibition of ERK1/2 and MAPK activities." (PMID 26010068, 2015). "HIF1α accumulation can also take place in presence of enhanced reactive oxygen species (ROS) and NF-κB in melanoma, both being commonly deregulated in this cancer type." (PMID 26000250, 2015). "As an example, protein expression of HIF1α is strong in melanoma cells predominantly expressing HIF1α-785, a splice isoform lacking a crucial part of the oxygen-dependent degradation domain." (PMID 26000250, 2015). "Given the relationship between HIF-1α and melanoma progression, this transcription factor is an attractive target for small molecule inhibitors." (PMID 26547841, 2015). "The lowest concentration of AA (5 μM) dramatically decreased the normoxic expression of HIF-1α protein in this human melanoma cell line." (PMID 26547841, 2015). "The compensatory pathways encompass a ROS-dependent activation of HIF-1α leading to high levels of glycolysis followed by a high dependence on glutamine use for melanoma growth and survival." (PMID 26713093, 2015). "STAT3 has been shown to increase HIF-1α levels by extension of protein half-life but also induction of HIF-1α transcription in human and mouse melanoma cells." (PMID 24743777, 2014). "On the other-hand, in a separate in vitro study, we observed that NLGP can directly modulate B16 melanoma tumor cells by reducing HIF1α and VEGF in normoxic as well in hypoxic condition (unpublished observation)." (PMID 25391149, 2014). "In melanoma cells, hypoxia-inducible factor (HIF-1α)-mediated transcriptional repression of ASS1 has been observed." (PMID 25164070, 2014). "Expression of MITF has been associated with proliferation and survival of melanoma cells via its target genes CDK2, Bcl-2, livin, c-met, and HIF1α." (PMID 23349796, 2013).
melanoma (continued). "Specifically, melanoma mice accumulate fumarate, and when the metabolite fumarate is increased, it inhibits PHDs (prolyl hydroxylases), leading to reduced hydroxylation of HIF-1α, which then stabilizes and activates the protein in thyroid carcinoma." (PMID 24958263, 2013). "A pertinent molecule for melanoma, HIF-1α is involved in suppressing OXPHOS, upregulates the metabolic program involved in glycolysis, and shows an association with overall worse prognosis in multiple cancers." (PMID 22912665, 2012). "Intriguingly, endothelins are among the factors with the ability to activate HIF-1α under normoxic conditions in melanoma and ovarian carcinoma cells." (PMID 22384254, 2012). "In the hypoxic microenvironment, melanoma cells increase HIF-1α expression and induce the formation of VM channels to acquire an adequate blood supply." (PMID 22357313, 2012). "In vivo treatment with melanoma-derived exosomes promotes HIF-1α mRNA expression in sentinel lymph nodes, highlighting the importance of further studies into exosome-mediated hypoxic signalling." (PMID 22998595, 2012). "We observed a relatively high VEGF-A expression under normoxic conditions in the B16F10 melanoma cells which suggests some kind of HIF-1α stabilization." (PMID 23077404, 2012). "We further show that Elesclomol upregulates hypoxia inducible factor 1-α (HIF-1α), and that prolonged exposure of melanoma cells to this drug leads to selection of melanoma cells with high levels of glycolysis." (PMID 22912665, 2012). "The second melanoma cell population resides in hypoxic areas, upregulates the HIF-1α glycolytic program, and releases lactate and hydrogen ions to maintain normal pH." (PMID 23043612, 2012). "Our results show that ET-1 promoted an increase in the levels of HIF-1α in astrocytes under normoxic conditions, as it has been previously shown in melanoma and ovarian carcinoma cells." (PMID 22384254, 2012). "Under already hypoxic conditions, treatment with 10 times the human equivalent of bevacizumab induced an increase of HIF-1α protein in B16F10 melanoma cells in comparison to the control." (PMID 23077404, 2012). "Efficiency of HIF1α silencing was determined analyzing HIF1α mRNA levels by quantitative RT-PCR, being this higher than 80% in primary melanocytes and SBcl2 melanoma cells." (PMID 22457728, 2012). "Since it has been reported that HIF-1α increases LDHA expression, we also determined HIF-1α expression in the nevus>melanoma TMA." (PMID 23043612, 2012). "ADI-PEG20 treatment down-regulates the expression of HIF-1α but up-regulates c-Myc in culture melanoma cells." (PMID 21152246, 2010). "Hypoxia independent expression of HIF-1α is thought to be regulated by growth signaling pathways and the majority of melanomas have constitutively active ERK1/2 MAPK pathway due to BRAF or N-Ras mutations." (PMID 19919690, 2009). "At least in the final stages of our melanoma we found an increases of carbonic anhydrase protein levels, an enzyme induced by hypoxia and a sensor of HIF1α transcription factor activity." (PMID 19682397, 2009). "All melanoma cell lines had increased expression of HIF-1α mRNA relative to normal human melanocytes." (PMID 19919690, 2009). "Knockdown of HIF-1α expression by siRNA in the MET WM9 melanoma cell line resulted in a large decrease in both soft agar colony formation and matrigel invasion relative to cells treated with non-specific siRNA." (PMID 19919690, 2009). "We found that HIF-1α protein and RNA is expressed under normoxic conditions in several human melanoma cell lines and that the levels of HIF-1α expression correlates with the stage of cancer from which the melanoma cell line was established." (PMID 19919690, 2009). "The SbCl2 radial growth phase melanoma cells have low levels of HIF-1α protein expression and a limited capacity to form colonies in soft agar and to invade through Matrigel." (PMID 19919690, 2009).
melanoma (continued). "We found that the increased HIF-1α protein in the melanoma cells was correlated with an increase in HIF-1α mRNA." (PMID 19919690, 2009). "Manipulation of HIF-1α expression in several of our melanoma cell lines suggests that this transcription factors regulates, in part, anchorage-independent growth and Matrigel invasion." (PMID 19919690, 2009). "Here, we show that in human melanoma cells, the oxygen-labile HIF-1α protein as well as its mRNA is expressed endogenously under normoxic conditions." (PMID 19919690, 2009). "In this study, we examined the normoxic expression and biological functions of HIF-1α in human melanoma." (PMID 19919690, 2009). "How this alternatively spliced isoform of HIF-1α mRNA is increased in melanoma is currently under investigation." (PMID 19919690, 2009). "In conclusion, HIF-1α is overexpressed, in melanoma cell lines under normoxic conditions in a manner that correlates with the aggressiveness of the tumor from which the cell line was established." (PMID 19919690, 2009). "We examined the biological consequences of HIF-1α FL and 785 splice variant gain of function and HIF-α FL loss of function in selected human melanoma cells." (PMID 19919690, 2009). "We also detected expression of a HIF-1α mRNA splice variant that lacks part of the oxygen-dependent regulation domain in WM1366 and WM9 melanoma cells." (PMID 19919690, 2009). "Overall our data suggest that increased HIF-1α expression under normoxic conditions contributes to some of the malignant phenotypes exhibited by human melanoma cells." (PMID 19919690, 2009). "In addition, HIF-1α transcription in the melanoma cell line B16-F10 results in an increase in tumor-infiltrating NK and CD8+ T cells." (PMID 40430040, 2025). "Interestingly, while ASS1 loss is due to promoter methylation in MPM cells, reduced ASS1 expression has been shown to be mediated by c-Myc and HIF-1α in other cancers including melanoma." (PMID 39758821, 2025). "In B16 cells, Rg3 inhibits VEGF expression by suppressing HIF-1α, attenuates the proliferation and migration of vascular endothelial cells, as well as reduces melanoma-induced angiogenesis, thereby effectively inhibiting melanoma growth and metastasis." (PMID 41585262, 2025). "IF analysis on bone tissue showed increased Hif1α expression levels in the melanoma group." (PMID 39814705, 2025). "The relationship between mitochondrial ROS and HIF-1α has been largely investigated in melanoma." (PMID 40721981, 2025). "To investigate the potential mutual regulatory interactions between HIF1 activation and CypD suppression, we exposed melanoma cells to mild hypoxia (1% O2), which not only resulted in HIF1α stabilization but also led to reduced expression of CypD at both the protein and mRNA levels." (PMID 40701956, 2025). "Thus, our results show that HIF1α induces expression of miR-23a and miR-27, which suppress CypD expression in melanoma cells, indicating a reciprocal regulatory loop involving HIF1α stabilization and CypD suppression." (PMID 40701956, 2025). "In conditions of hypoxia, HIF-1α is translocated into the nucleus and activates the expression of genes involved in angiogenesis together with genes involved in metabolism, cellular proliferation, and metastasis, leading to melanoma progression." (PMID 40867317, 2025). "HDAC8 promotes melanoma growth and migration by acting HIF-1α." (PMID 40573249, 2025). "The HDAC8 promotes the expression of HIF-1α target genes, such as hexokinase 2 (HK2) and glucose transporter protein 1 (GLUT1), by upregulating HIF-1α expression levels and elevating HIF-1α transcriptional activity, which can promote the proliferation and metastasis of melanoma cells." (PMID 39876842, 2024). "The effects of RAF/RAS mutations on the melanoma metabolism include stimulating MYC and HIF1α signaling to promote glycolysis, as well as the inhibition of mitochondrial oxidative phosphorylation (OXPHOS) by repressing MITF and PGC1α, and promoting fatty acid synthesis." (PMID 38397192, 2024).
melanoma (continued). "Furthermore, HIF-1α is constitutively activated in melanoma under both normal and hypoxic conditions and is accompanied by increased glycolysis." (PMID 39728923, 2024). "All these results demonstrated that the in vitro oxygenation of PCC 7942 could not only alleviate intracellular hypoxic microenvironment, but also effectively block the upstream pathway of HIF-1α-dependent genes closely related to melanoma metastasis." (PMID 38280861, 2024). "Moreover, studies have demonstrated that the PI3K/AKT/mTOR signaling pathway can affect the proliferation and metastasis of melanoma by altering the expression of HIF-1α." (PMID 38771435, 2024). "ELP3 and CTU1/2 were shown to enhance glycolysis in melanoma cells by up-regulating hypoxia-inducible factor 1 subunit alpha (HIF1A) translation through codon-dependent regulation, contributing to their resistance to RAF inhibitors such as vemurafenib or dabrafenib." (PMID 38476632, 2024). "Indeed, suppressing of PGC1α-dependent oxidative metabolism activates glycolysis via HIF1α as a compensatory survival mechanism in melanomas." (PMID 38774408, 2024). "Indeed, activation of HIF1A has been shown to play a major role in melanoma initiation, invasion and metastasis." (PMID 38902533, 2024). "Additionally, immunofluorescence staining of human melanoma tissue showed an induction of the AP2ε protein expression in HIF1-α positive nuclei." (PMID 38773108, 2024). "This might be due to progression of melanoma to a later stage, where additional mutations are acquired to cope with the stress induced by NLGN4X loss whereupon HIF1A activation becomes persistent." (PMID 38902533, 2024). "This phenotype may also occur in melanoma, where miRNA-mediated changes in HIF-1α and MITF expression have been reported." (PMID 39594467, 2024). "PHD2, which destabilizes HIF-1α, is downregulated in melanomas." (PMID 36901857, 2023). "Moreover, HIF1A expression was positively correlated with HDAC8 expression in the samples from patients with melanoma." (PMID 36831463, 2023). "Furthermore, HDAC8 is correlated with HIF1A expression and poor prognosis in samples from patients with melanoma." (PMID 36831463, 2023). "Therefore, we suggest HDAC8 as a novel regulator of HIF-1α and a therapeutic target for melanoma treatment." (PMID 36831463, 2023). "To conclude, we demonstrated the epigenetic regulation of HIF-1α in melanoma." (PMID 36831463, 2023). "Another mechanism of angiogenesis stimulation due to Cx43 loss relies on the massive production of pro-angiogenic factors due to the elevated levels of hypoxia-induced factor alpha 1 (HIF1a), as Cx43 is responsible for HIF1a ubiquitination and degradation indicated in melanoma." (PMID 36829482, 2023). "Given that ROR2 expression reportedly undergoes HIF-1α -mediated upregulation in hypoxia, we tested whether increased ROR2 expression and VEGF secretion in BRAFV600E melanoma cells resulted from HIF-1α stabilization." (PMID 36539575, 2023). "HIF-1α is upregulated in melanoma and drives tumor progression." (PMID 36831463, 2023). "In addition, MITF upregulates HIF-1α to enhance melanoma cell survival by directly binding to the HIF-1α promoter." (PMID 36901857, 2023). "Furthermore, cAMP-mediated MITF expression transcriptionally activates HIF-1α in B16-F10 melanoma cells." (PMID 36901857, 2023). "Moreover, the treatment of melanoma-bearing mice with Acriflavine, which is reported to prevent the dimerization between HIF-1α and HIF-1β, led to an improvement in immunotherapy based on TRP-2 peptide vaccination and anti-PD-1 antibody." (PMID 37443821, 2023). "Considering the involvement of hypoxia in the immunosuppressive microenvironment of tumors, we provided evidence that deleting the transcriptional activity of HIF-1α decreased the tumor growth of a melanoma mouse model and increased the infiltration of CD45+, NK, CD4+, and CD8+ cells." (PMID 37443821, 2023).